MIR6501 (microRNA 6501)
Synonyms: hsa-mir-6501; mir-6501
Gene: MicroRNA gene on chromosome 21 (33,550,662 to 33,550,728, forward strand). Ensembl gene ENSG00000284448.
Homologues: Orthologues: macaque MIR6501 (100% identical).